ATF4 (activating transcription factor 4)
Diseases named in the same sentence as ATF4 in open-access papers (continued):
Sharing a sentence is not in itself a finding about the gene and the disease.
Insulin resistance (16 papers, 2015 to 2025). Increased resistance towards insulin, that is, diminished effectiveness of insulin in reducing blood glucose levels. "It is unclear why ATF4 expression in the hypothalamus causes insulin resistance but in the muscle increases insulin sensitivity." (PMID 28860159, 2017). "Furthermore, inhibition of ATF4 in the hypothalamus reverses insulin resistance caused by ER stress in the brain, suggesting that ER stress causes hepatic insulin resistance through ATF4." (PMID 28860159, 2017). "While PDX1 expression itself is not induced by stress, it regulates islet compensation for HFD-induced insulin resistance, in part through direct transcriptional regulation of Atf4 and Wsf1." (PMID 32093016, 2020). "Hypothalamic overexpression of ATF4 induces hepatic insulin resistance, which is reversed by the inhibition of hypothalamic S6K." (PMID 30875909, 2019). "On the other hand, suppression of hypothalamic ATF4 reverses ER stress-induced hepatic insulin resistance." (PMID 30875909, 2019). "Overexpression of ATF4 in the hypothalamus induces hepatic insulin resistance in mice, and inhibition of ATF4 by expressing dominant-negative ATF4 has the opposite effect." (PMID 28860159, 2017). "FTO and ATF4 were negatively correlated with adiposity and insulin resistance indices." (PMID 40806129, 2025). "If Sephin1 acts on these tissues, then enhanced ATF4 expression in these tissues may lead to insulin resistance." (PMID 34547510, 2021). "MEG3 enhances hepatic insulin resistance via miR-214/ATF4 axis." (PMID 31195367, 2019). "Interestingly, overexpression and inhibition of ATF4 in the hypothalamus induces hepatic insulin resistance and improves hepatic insulin sensitivity, respectively." (PMID 28555094, 2017). "Additionally, expression of ATF4 in the hypothalamus induces insulin resistance, whereas ATF4 expression in muscle protects against diet-induced insulin resistance, suggesting that even the same TF exerts responses depending on when and where it is expressed." (PMID 28860159, 2017). "Interestingly, we previously reported hepatic insulin resistance in rats on a fcHFHS diet, which could well be related to the observed increase in hypothalamic ATF4 mRNA." (PMID 28555094, 2017). "In insulin-resistant (IR) children, MEG3, ATF4, FTO, ACACA, and SREBP1 were reduced, while FASN was increased." (PMID 40806129, 2025). "Notably, β cells from BoNT/BTan mice exhibited elevated expression of the early onset ER-stress marker Atf4, suggesting that the increased insulin secretion observed in these mice following insulin resistance may trigger an ER unfolded protein response and ER stress." (PMID 39047908, 2024). "The ER stress markers (ATF4, IRE-1α, PERK, sXBP-1, and CHOP) are crucial proteins involved in the pathogenesis of inflammation and insulin resistance; hence, we investigated their gene expression in the liver of experimental rats." (PMID 35779187, 2022). "LncRNA MEG3 contributes to hepatic insulin resistance in DM by sequestering miR-214 and upregulating the transcriptional factor ATF4 (activating transcription factor 4), which promotes gluconeogenesis through upregulation of glucose-6-phosphatase and phosphoenolpyruvate carboxy kinase enzymes." (PMID 36010595, 2022). "In addition, a recent study showed that ATF4 deletion in AGRP neurons of the hypothalamus specifically protects against high fat diet induced weight gain and insulin resistance." (PMID 28555094, 2017).
non-small cell lung carcinoma (16 papers, 2017 to 2025). A group of at least three distinct histological types of lung cancer, including non-small cell squamous cell carcinoma, adenocarcinoma, and large cell carcinoma. "In this study, we investigated the function of ATF4 in non-small cell lung cancer and its molecular regulation." (PMID 33628101, 2021). "Human non-small cell lung cancer with high NRF2 protein expression displayed significantly higher expression of ATF4, PHGDH, PSAT1, and SHMT2, which was significantly related to poorer prognosis and higher tumor grade." (PMID 32226297, 2020). "A previous study has shown that ATF4 transcriptionally activates serine biosynthetic genes in response to serine starvation in non-small cell lung cancer cells." (PMID 29216929, 2017). "In addition, TIPRL overexpression is found to induce autophagy and accelerate growth through the eIF2α-ATF4 pathway in non-small cell lung cancer." (PMID 32719745, 2020). "Furthermore, PHGDH, PSAT1, PSPH, and SHMT have been shown to be direct transcriptional targets of ATF4 which was transcriptionally activated by NRF2 in a non-small-cell lung cancer model." (PMID 31615983, 2019). "ATF4 transcriptionally activates serine biosynthetic genes in response to serine starvation in non-small cell lung cancer, and additionally, it has been shown to play a crucial role in the regulation of PSAT1 after OSN (Oct4, Sox2, and Nanog) was expressed in mouse embryonic stem cells." (PMID 29216929, 2017). "Moreover, ATF4-mediated upregulation of amino acid transporters facilitates increased nutrient uptake under chemotherapeutic stress (Activated amino acid response pathway generates apatinib resistance by reprograming glutamine metabolism in non-small-cell lung cancer)." (PMID 40830338, 2025). "LncRNAs have recently emerged as pivotal regulators of ATF4 signaling in respiratory diseases, including lung adenocarcinoma (LUAD), non-small cell lung cancer (NSCLC), pulmonary fibrosis and acute lung injury (ALI)." (PMID 40777108, 2025). "Another example is NFE2-like bZIP transcription factor 2 (NRF2), an essential transcription factor frequently deregulated in non-small cell lung cancer (NSCLC), which regulates SSP enzymes by targeting ATF4." (PMID 36699468, 2022). "Additionally, PHGDH has been identified as a direct transcriptional target of ATF4, which was found to be transcriptionally activated by NRF2 in a non-small cell lung cancer model." (PMID 40102981, 2025).
atherosclerosis (14 papers, 2013 to 2026). A disease characterized by the build-up of fatty material and calcium deposition in the arterial wall resulting in partial or complete occlusion of the arterial lumen. "Studies have indicated dual roles of ATF4 in regulating ferroptosis in different conditions, but its exact effect on ferroptosis in atherosclerosis still remains to be elucidated." (PMID 41561820, 2026). "Together, these findings demonstrate that activation of the ATF4 branch of the ER stress signaling pathway mediates the impairment of the protective NET-induced DNase response in atherosclerosis." (PMID 41031413, 2025). "We previously established that increased intracellular cholesterol activates PERK/ATF4/KLF4 signaling and is responsible for a component of atherosclerosis-associated phenotypic modulation of SMCs." (PMID 37937642, 2023). "Induction of ATF4 was also observed in a number of human disease states accompanied by oxidative stress including atherosclerosis, allergic contact dermatitis, and sporadic Alzheimer’s disease." (PMID 29180630, 2017). "However, aortic explants from the ISRIB-treated group demonstrated increased release of DNase in the supernatant in response to NETs and increased efficiency of clearance of NETs, suggesting that ATF4 inhibition by ISRIB increases the NET-induced DNase response in atherosclerosis." (PMID 41031413, 2025). "ER stress–related gene expression, including ATF4 and CHOP mRNA levels, is elevated in the endothelium of coronary artery regions that are prone to atherosclerosis versus regions that are resistant to atherosclerosis." (PMID 38175710, 2024). "ATF4-miR-552-SKI axis played critical roles in the proliferation and migration of HBVSMCs and mVSMCs, which were closely involved in atherosclerosis (AS)." (PMID 35857794, 2022). "Our results on CHOP induction in response to heme correlates well with studies reporting activation of PERK/eIF2α/ATF4/CHOP pathway in a response to oxidized LDL, which, like heme, is considered a pathological factor of atherosclerosis." (PMID 30515102, 2018). "Recently, a study of atherosclerosis showed that laminar flow protected ER stress-induced cleaved forms of PARP-1 and caspase-3 and inhibited the ER stress-induced p-eIF2α, ATF4, CHOP, spliced XBP-1, ATF6, and JNK pathways to protect endothelial cells from apoptosis." (PMID 31506423, 2019). "Furthermore, TFs, including nuclear factor kappa beta (NF-κB), PU.1, the Ets-1 family, activator protein 1 (AP1), Krϋppel-like factor 2 (KLF2), zinc fingers and homeoboxes 2 (Zhx2), and activating transcription factor 4 (ATF4), play a critical role in atherosclerosis." (PMID 35645372, 2022).
esophageal squamous cell carcinoma (14 papers, 2014 to 2025). Esophageal squamous cell carcinoma (ESCC) is a type of esophageal carcinoma (EC) that can affect any part of the esophagus, but is usually located in the upper or middle third. "Previous studies in our laboratory unveiled that ATF4 transcriptionally activated Noxa in esophageal squamous cell carcinoma cells after treated by small-molecule compound MLN4924." (PMID 33995110, 2021). "ATF4 hasbeen reported to promote esophageal squamous cell carcinoma invasion and metastasis, whereas the effect of ATF3 on metastasis in different types of cancer remains controversial." (PMID 26913720, 2016). "Finally, increased expression of ATF4 in esophageal squamous cell carcinoma correlates with invasion and metastasis, an effect attributed to increased transcription of MMP-2 and MMP-7." (PMID 27802179, 2016). "Therefore, interventions that are based on disrupting stress-induced ATF4 expression in cancer cells may be helpful in developing effective treatments of esophageal squamous cell carcinoma." (PMID 25078779, 2014). "In esophageal squamous cell carcinoma (ESCC), BC200 was shown to upregulate ATF4 expression, enhancing the migration and invasion of cancer cells under nutrient-stressed conditions." (PMID 40777108, 2025). "In esophageal squamous cell carcinoma (ESCC), overexpression of ATF4, a PERK effector, is involved with increased expression of MMP-2 and MMP-7 to promote invasion and metastasis of ESCC in vitro and in vivo." (PMID 33746610, 2021). "Chen et al12 recently found that in oesophageal squamous cell carcinoma (ESCC) cells, MLN4924‐induced Noxa activation was dependent on ATF4, a well‐known CRL substrate, and down‐regulation of ATF4 completely blocked the induction of Noxa." (PMID 30341788, 2019). "ATF4 activates the transcription factor CHOP and then transcriptionally activates death receptor 5 (DR5) and caspase 8, which ultimately induces the extrinsic apoptosis of esophageal squamous cell carcinoma (ESCC) cells." (PMID 37006236, 2023).
glaucoma (14 papers, 2020 to 2025). Increased pressure in the eyeball due to obstruction of the outflow of aqueous humor. "For our identified driving factor ATF4, it has been confirmed in previous studies that it can cause glaucoma by promoting ER client protein load and regulating trabecular meshwork remodeling." (PMID 34926471, 2021). "Recent studies found the upregulation of ATF4 in the trabecular meshwork in glaucoma patients, and the persistent activation of ATF4 during chronic ER stress was associated with the development of glaucoma." (PMID 37297954, 2023). "We next examined whether ATF4 leads to functional and structural loss of RGCs, as is observed in glaucoma patients." (PMID 33154371, 2020). "Here, we show that RGCs have activated ATF4-CHOP signaling in human glaucoma and in response to ocular hypertension in mice." (PMID 40076484, 2025). "An alternative study supported the role of ATF4 in glaucoma, as its deletion from retinal ganglion cells was found to promote axon survival and rescue glaucomatous neurodegeneration." (PMID 41515893, 2025). "Here, we report that the ATF4-CHOP pathway is activated in the retinas of human glaucoma donor eyes and a mouse model of ocular hypertension." (PMID 40076484, 2025). "Here, the authors show that inhibition of chronic ER stress-induced ATF4-CHOP-GADD34 signaling pathway rescues pathology in mouse models of glaucoma, thus suggesting a possible treatment strategy." (PMID 33154371, 2020). "Consistent with this, we observed that both genetic and pharmacological knockdown of the ATF4 pathway rescues mouse models of glaucoma." (PMID 33154371, 2020). "In summary, our studies indicate that ATF4–CHOP–GADD34 signaling pathway is induced in glaucoma, which promotes protein synthesis and ER client protein load, inducing TM cell death and IOP elevation." (PMID 33154371, 2020). "Given its role in glutamine metabolism in the text, ATF4 may pose a synergistic target in augmenting glutaminolysis in glaucoma and altering glaucomatous neurodegeneration." (PMID 41515893, 2025). "ATF4 levels are found to be elevated in the TM tissues of 5-week Dex-treated mice, indicating that this model may appropriately recapitulate the glaucoma pathology due to ROS elevation, and SA-9 may able to scavenge them." (PMID 33917924, 2021). "Since similar induction of ATF4, CHOP, and GADD34 was also associated with IOP elevation in mouse model of Dex-induced ocular hypertension and in human primary TM cells from glaucoma donors, it is likely that induction of chronic ER stress is truly a key feature of glaucomatous TM pathology." (PMID 33154371, 2020). "Importantly, increased ATF4 and CHOP expression have been observed in TM from patients with POAG, suggesting that the activation of ATF4/CHOP pathway is implicated in TM cell injury and IOP increase in human glaucoma." (PMID 35346303, 2022). "The study demonstrated that valdecoxib inhibits the ATF4-CHOP pathway in “I/R-induced glaucoma-like” damaged cells, providing potential insights into its therapeutic efficacy in glaucoma management." (PMID 37508003, 2023). "Studies on TMCs have demonstrated the involvement of the PERK-eIF2α-ATF4-CHOP cascade in glaucomatous TM, both in human and murine cells, highlighting the activation of this pathway in glaucoma." (PMID 37508003, 2023). "The chronic ER stress-inducible pro-apoptotic markers ATF4 and CHOP are significantly increased in mouse models of glaucoma and in TM tissues from POAG donors." (PMID 34830390, 2021). "Here, we report that the chronic endoplasmic reticulum (ER) stress-induced ATF4-CHOP-GADD34 pathway is activated in TM of human and mouse glaucoma." (PMID 33154371, 2020). "Here, we show that chronic ER stress-induced ATF4–CHOP–GADD34 signaling axis is activated in the TM of mouse and human glaucoma." (PMID 33154371, 2020). "To test our hypothesis, we examined whether ATF4 and CHOP are induced in RGCs of glaucoma donor eyes and a mouse model of ocular hypertension." (PMID 40076484, 2025).
glaucoma (continued). "To evaluate whether chronic ER stress-induced transcriptional factors, activating transcription factor 4 (ATF4), and C/EBP homologous protein (CHOP) are induced in RGCs; we utilized human donor tissue and the microbead occlusion model of glaucoma." (PMID 40076484, 2025). "Additionally, inducing ER stress by overexpressing ATF4 led to TM dysfunction, resulting in elevated IOP and glaucomatous neurodegeneration in a mouse glaucoma model." (PMID 40385286, 2025). "Notably, genetic depletion or pharmacological inhibition of ATF4-CHOP-GADD34 pathway prevents TM cell death and rescues mouse models of glaucoma by reducing protein synthesis and ER client protein load in TM cells." (PMID 33154371, 2020). "We observed that glaucoma causing factors significantly increased chronic ER stress markers, CHOP and ATF4 but not GRP78 in the TM tissues of corneoscleral segments." (PMID 32579557, 2020). "In the present study, we further examined whether ATF4–CHOP–GADD34 signaling axis is also activated in TM cells and tissues of human and mouse glaucoma." (PMID 33154371, 2020). "It is likely that increased expression of CHOP in TM is involved in key glaucoma pathology, but expression of CHOP alone is not sufficient to cause these pathologies since it lacks other interacting factors of the chronic ER stress pathway including ATF4." (PMID 33154371, 2020). "Although both ATF4 and CHOP appeared to increase in the RGCs of glaucoma donor eyes, we observed that immunostaining for CHOP but not ATF4 was significantly elevated in the RGCs of human glaucoma patients." (PMID 40076484, 2025).